ATF1 (activating transcription factor 1)
Diseases named in the same sentence as ATF1 in open-access papers (continued):
Sharing a sentence is not in itself a finding about the gene and the disease.
nasopharyngeal carcinoma (6 papers, 2016 to 2022). A carcinoma arising from the nasopharyngeal epithelium. "ATF1 overexpression and hyperphosphorylation are associated with the clinical stage of nasopharyngeal carcinoma." (PMID 35397606, 2022). "Our study aims to investigate the association between ATF1 rs11169571 and nasopharyngeal carcinoma's risk." (PMID 30905073, 2019). "All in all, our study suggested that ATF1 rs11169571 polymorphism was associated with nasopharyngeal cancer's risk in a Chinese population in Guangdong Province." (PMID 30905073, 2019). "The transcriptional activity of ATF1 was found to be regulated by Thr184 phosphorylation in nasopharyngeal carcinoma." (PMID 35397606, 2022). "Overexpression of ATF1 in nasopharyngeal carcinoma was positively correlated with the expression of MMP2." (PMID 35397606, 2022). "In previous work, we identified ATF1 Thr184 as its new phosphorylation site, which mediates the interaction between ATF1 and Pin1, enhances ATF1 transcription activity and the development of nasopharyngeal carcinoma." (PMID 35397606, 2022). "Our previous work reported activating transcription factor 1 (ATF1) is a promotive factor of nasopharyngeal carcinoma (NPC) tumorigenesis." (PMID 30905073, 2019). "ATF1 plays an important role in cancer progression and was found to promote nasopharyngeal carcinoma (NPC) tumorigenesis in our previous study." (PMID 30905073, 2019). "The ATF1 rs11169571 might be considered to be a potential biomarker for nasopharyngeal cancer risks." (PMID 30905073, 2019). "Overexpression of ATF1 has been observed in nasopharyngeal carcinoma (NPC), gastrointestinal clear cell sarcoma, and other cancers in various investigations." (PMID 35578572, 2022). "The function of activating transcription factor 1 (ATF1) and the mechanism about why ATF1 was over-phosphorylated in nasopharyngeal carcinoma (NPC) progression is completely undiscovered." (PMID 28032861, 2016).
soft tissue sarcoma (6 papers, 2012 to 2022). A malignant neoplasm arising from muscle tissue, adipose tissue, blood vessels, fibrous tissue, or other supportive tissues excluding the bones. "Therefore, we support the hypothesis that CCS belongs to the soft tissue sarcoma family and that the melanin synthesis is due to the specific action of the chimeric EWF/ATF1 protein via MITF activation." (PMID 22693489, 2012).
leukemia (5 papers, 2011 to 2025). A malignant (clonal) hematologic disorder, involving hematopoietic stem cells and characterized by the presence of primitive or atypical myeloid or lymphoid cells in the bone marrow and the blood. "Rothem et al26 have reported that reduced expression of transcription factors as CREB1, ATF1, USF1, FOS, JUN, Sp3, and Sp1 is responsible for a major decrease in RFC mRNA expression in the CCRF‐CEM and derived human leukemia cell lines." (PMID 32614991, 2020).
soft tissue tumors (5 papers, 2011 to 2025). "As a result, in-frame EWSR1::ATF1 produces the oncogenic EWSR1::ATF1 chimeric protein, which is the cytogenetic hallmark of certain soft-tissue tumors and is often found as the only chromosomal abnormality in the affected neoplasms." (PMID 39769457, 2024). "We herein describe a unique cohort of soft tissue neoplasms characterized by epithelioid/round cell morphology, unusual immunophenotype, and recurrent EWSR1::ATF1 fusions, all occurring in extra-abdominal deep soft tissue or bone sites." (PMID 39031200, 2024).
malignant mesothelioma (4 papers, 2022 to 2024). A malignant neoplasm of the pleura or peritoneum, arising from mesothelial cells. "Integrations of clinical genomics, pathology and FISH have revealed that EWSR1-fusions with the CREB family member ATF1 (EWSR1-ATF1) are also drivers in malignant mesothelioma (MM), in addition to CCS." (PMID 38946804, 2024). "Since these rearrangements are not frequently seen in malignant mesothelioma with adult onset, which is believed to be tightly correlated with asbestos or radiation exposure, the EWSR1::ATF1-positive pediatric cases are believed to present a distinct subtype of malignant mesotheliomas." (PMID 39769457, 2024). "We found a female predominance, except for cases harboring NR4A3 and SUFU malignant mesothelioma, and most patients were around 60 years at diagnosis, but those harboring ALK or EWSR1/FUS::ATF1 gene fusions were younger." (PMID 39059063, 2024). "Pediatric malignant mesothelioma, which is usually peritoneal and pericardial, is also known to harbor EWSR1::ATF1 rearrangements." (PMID 39769457, 2024).
mesothelioma (4 papers, 2021 to 2026). A usually malignant and aggressive neoplasm of the mesothelium which is often associated with exposure to asbestos. "Among the non-mesenchymal categories, EWSR1::ATF1 fusions define the majority of hyalinizing clear cell carcinoma of head and neck and have been reported also in a rare subset of mesotheliomas." (PMID 39031200, 2024).
gastric cancer (3 papers, 2022 to 2025). A primary or metastatic malignant neoplasm involving the stomach. "In this study, we found that the mRNA level of ATF1 was higher in gastric cancer and associated with patient’s survival using TCGA data." (PMID 35397606, 2022). "Moreover, the Kaplan–Meier curve showed that a higher mRNA level of ATF1 was associated with poor survival of gastric cancer using TCGA data." (PMID 35397606, 2022). "Combined mRNA expression of MMP2 and ATF1 was associated with gastric cancer survival." (PMID 35397606, 2022). "The wound healing assay showed the gastric cancer cells transfected with the ATF1-T184D mutant plasmids had better migration ability in both cells." (PMID 35397606, 2022). "The correlation between ATF1 mRNA and the mRNA levels of MMP2 was examined in gastric cancer cell lines and HEK293 cells." (PMID 35397606, 2022). "Furthermore, only a few of the top twenty transcription factors identified are expressed among the gastric cancer cell lines and do not appear to be greatly affected by DCB treatment, including RARA, ATF1, THRA, and MEF2A." (PMID 41280003, 2025).
Hypertension (3 papers, 2018 to 2021). The presence of chronic increased pressure in the systemic arterial system. "The ATF1 rs11169571 allele is involved in the pathogenic mechanism of essential hypertension by altering the hsa-miR-1283 binding site." (PMID 30445764, 2018). "An SNP at the 3’-UTR of the ATF1 (activating transcription factor 1) gene altered the posttranscriptional regulation of this gene by miRNAs, leading to essential hypertension with high ATF-1 expression." (PMID 30445764, 2018). "A previous study showed that hsa-mir-1273 g-3p, hsa-mir-4789-3p and ATF1 could involved in hypertension, but these markers might be responsible for progression of HF." (PMID 34218797, 2021).
lymphoma (3 papers, 2018 to 2022). A malignant (clonal) proliferation of B- lymphocytes or T- lymphocytes which involves the lymph nodes, bone marrow and/or extranodal sites. "ATF1 expression was increased in lymphoma cells and activated lymphocytes, suggesting that ATF1 may play an important role in cell growth and differentiation." (PMID 35397606, 2022).
acute myeloid leukemia (2 papers, 2008 to 2025). Acute myeloid leukemia (AML) is a group of neoplasms arising from precursor cells committed to the myeloid cell-line differentiation. "Four of the seven dysregulated TFs, Atf1, Fos, Rxra and Stat5b, have been previously associated with acute myeloid leukemia, and ninety-six genes that were differentially expressed in APL were identified as targets of these TFs." (PMID 18291030, 2008). "Additional regulators include aryl hydrocarbon receptor nuclear translocator in acute myeloid leukemia (AML), CREB-1, activating transcription factor 1 (ATF-1), and HIF-1α." (PMID 40722952, 2025).
mucoepidermoid carcinoma (2 papers, 2023 to 2024). A carcinoma morphologically characterized the presence of cuboidal mucous cells, goblet-like mucous cells, squamoid cells, cystic changes, and a fibrotic stromal formation. "These include fusions of the ETV6 gene in secretory carcinoma (SC), MYB/MYBL1::NFIB in adenoid cystic carcinoma (AdCC), CRTC1/CRTC3::MAML2 in mucoepidermoid carcinoma (MEC), and EWSR1::ATF1 in hyalinizing clear cell carcinoma as the most frequent and best characterized gene fusions." (PMID 38217715, 2024).
osteoporosis (2 papers, 2022 to 2023). A condition of reduced bone mass, with decreased cortical thickness and a decrease in the number and size of the trabeculae of cancellous bone (but normal chemical composition), resulting in increased fracture incidence. "Knockdown of ATF1 might be a promising strategy to manage osteoporosis." (PMID 35568813, 2022). "Therefore, this study contributes a novel pathway, ATF1/miR-214-5p/ITGA7 axis, involved in the regulation of bone resorption, which might provide a new option for the treatment of human osteoporosis." (PMID 35568813, 2022).
seminoma (2 papers, 2026). A radiosensitive malignant germ cell tumor found in the testis (especially undescended), and extragonadal sites (anterior mediastinum and pineal gland). "Previously misclassified as Sertoli cell tumor, not otherwise specified, or as seminoma, this entity has emerged as a distinct clinicopathologic and molecular subtype defined by recurrent EWSR1::ATF1 gene fusions and a potentially aggressive clinical course." (PMID 41898873, 2026).
breast tumors (1 paper, 2023). "Notably, proximity analyses between neural markers and nuclear phospho-CREB1/ATF1 indicate that higher cancer-cell CRE activity is present in the region proximal to neural signals (NF-L, TH and SYP positive area) in breast tumors." (PMID 37463926, 2023).
Cachexia (1 paper, 2020). Severe weight loss, wasting of muscle, loss of appetite, and general debility related to a chronic disease. "Of note, STAT3 and CEPBδ are among the differentially expressed ATF‐1 target genes induced by cachexia that respond only to AR‐42 treatment." (PMID 31930715, 2020).
central neurocytoma (1 paper, 2025). A benign brain tumor composed of neural elements which most often arise from the SEPTUM PELLUCIDUM and the walls of the lateral ventricles. "Interestingly, a single case of atypical central neurocytoma with EWSR1::ATF1 fusion and MUTYH G382D mutation (detected via NGS) achieved ~3 years of PFS with conventional glioma therapy in a 13-year-old patient." (PMID 40575153, 2025).
Cerebral ischemia (1 paper, 2016). Restriction of arterial blood supply to the brain associated with insufficient oxygenation to support the metabolic requirements of the tissue. "The experimental results indicated that PBX1 and ATF1, along with six other TFs, are putative target TFs for DHI-mediated protection against cerebral ischemia." (PMID 27431009, 2016).
depression (1 paper, 2025). "Through comprehensive molecular regulatory network analysis, transcription factors such as ATF1, IRF1, HBP1, DRAP1, TGIF2, and TFDP1 were identified as potential regulatory factors in depression, warranting further exploration." (PMID 40370590, 2025).
glioblastoma (1 paper, 2024). The most malignant astrocytic tumor (WHO grade IV). "In two cases, the identification of entity-specific fusions suggested a re-classification of a meningioma CNS-WHO grade 2 to intracranial mesenchymal tumor (ATF1::ESWR1 fusion) and glioblastoma to a polymorphous low-grade neuroepithelial tumor of the young (PLNTY, FGFR2::CTNNA3 fusion)." (PMID 39143272, 2024).
hematoma (1 paper, 2020). A hematoma is a collection of blood from a vascular structure into an extravascular space. "We show here that deletion of either ATF1 or AMPK impairs normal hematoma resolution in vivo, causing hematoma persistence with inflammation and oxidative stress." (PMID 32611235, 2020). "Taken together, these data demonstrate that both AMPK and ATF1 are required for normal hematoma resolution." (PMID 32611235, 2020). "In this study, we show that hematoma clearance in vivo and HO-1 induction by hemin are mediated by AMPK and by ATF1." (PMID 32611235, 2020). "Hematoma resolution required the signaling enzyme AMPK (AMP-activated protein kinase) and gene activation by ATF1 (activating transcription factor-1)." (PMID 32611235, 2020).
hyperlipidemia (1 paper, 2021).
hypopharyngeal carcinoma (1 paper, 2017). Carcinoma, predominantly squamous cell, arising from the epithelial cells of the hypopharynx. "Moreover, we identified several copy number variants (CNVs) genes were associated with hypopharyngeal carcinoma, one with amplification (ATF1) and two with deletions (CDKN2A, CDKN2B)." (PMID 29156722, 2017).
leiomyoma (1 paper, 2007). A well-circumscribed benign smooth muscle neoplasm characterized by the presence of spindle cells with cigar-shaped nuclei, interlacing fascicles, and a whorled pattern. "They included several genes such as NR2F1, PNN, Smad4, Smad5, STAT5B, JUN, TGIF2, and ATF1 that were over-expressed while RUNX3, STAT1, STAT6, EGR3, GAS7, Smad1, and EDF1 were underexpressed in leiomyomas as compared to keloid/incisional scars." (PMID 17718906, 2007).
leukopenia (1 paper, 2021). "We found that berbamine, a natural agent that has been used as a traditional medicine in clinics to ameliorate leukopenia caused by cancer radiotherapy and chemotherapy, could inhibit the induction of CREB/ATF1 phosphorylation by aspirin in HepG2 and Hep3B cells." (PMID 33917483, 2021).
liver cancer (1 paper, 2020). An epithelial or non-epithelial malignant neoplasm that arises from the liver. "In liver cancer, two lncRNAs GHET1 and CSMD1-1 stabilize activating transcription factor 1 (ATF1) mRNA expression or c-Myc protein respectively, by binding to its protein to regulate cancer cell migration and invasion." (PMID 33050646, 2020).
male fertility (1 paper, 2016). A fertility quality of inhering in a male by virtue of the bearer's disposition to initiate, sustain, or support reproduction. "Activation of the transcription factors CREB and ATF-1 is also of physiological significance for male fertility." (PMID 26938869, 2016).
mesothelial tumors (1 paper, 2024). "We demonstrated herein that EWSR1/FUS::ATF1 fused tumors should probably be considered as distinct mesothelial tumors." (PMID 39059063, 2024).
metabolic syndrome (1 paper, 2025). A cluster of metabolic risk factors for CARDIOVASCULAR DISEASES and TYPE 2 DIABETES MELLITUS. "Among these, several transcription factors stand out for their close connection to cyclic AMP signaling (ATF1, ATF3, and CREB1), although their relationship to metabolic syndrome and aging is less investigated." (PMID 40011442, 2025).
mucormycosis (1 paper, 2019). "atf1 and atf2 genes induce pathways related to virulence processes in mucormycosis." (PMID 30723131, 2019).
osteoarthritis (1 paper, 2019). A noninflammatory degenerative joint disease occurring chiefly in older persons, characterized by degeneration of the articular cartilage, hypertrophy of bone at the margins and changes in the synovial membrane. "Differences between treatments may be primarily attributed to metabolic regulators such as Pparg and Ppara as well as Atf1, and Atf2, which have been reported as being selectively under-expressed in RA synovial extracts even when compared to osteoarthritis (OA) controls." (PMID 31071076, 2019).
ovarian carcinoma (1 paper, 2018). A malignant neoplasm originating from the surface ovarian epithelium. "Another regulatory variant in ATF1 (rs11169571) was shown to increase breast/ovarian cancer risk through modifying miRNA binding." (PMID 29445242, 2018).
pancreatic cancer (1 paper, 2026). "We also emphasize that obesogenic mediators and stress neurotransmitters stimulate protein kinase signaling pathways, including PKA and PKD, which converge on CREB/ATF1 phosphorylation in pancreatic cancer cells." (PMID 41484057, 2026). "Since the phosphorylation of CREB and ATF1 is necessary for their activation as transcription factors, defining the upstream protein kinases that mediate CREB and ATF1 phosphorylation in pancreatic cancer cells is important." (PMID 41484057, 2026).
psoriasis (1 paper, 2024). An autoimmune condition characterized by red, well-delineated plaques with silvery scales that are usually on the extensor surfaces and scalp. "Along the same lines, a simplified version of the cAMP-signaling KEGG pathway focusing on the signal transduction relevant to psoriasis was created, and its analysis revealed SNPs within CBP, ATF1 and NFKBIA genes to be associated with the response to apremilast." (PMID 38540428, 2024).
testicular neoplasm (1 paper, 2024). Tumors or cancer of the TESTIS. "Finally, a distinctive aggressive testicular neoplasm carrying a EWSR1::ATF1 fusion has been reported recently under the descriptive name “inflammatory and nested testicular sex cord tumor”." (PMID 39031200, 2024).
thyroid cancer (1 paper, 2022). "ATF1 regulates the down-regulation of TSP-1, leading to increased aggressiveness of thyroid cancer cells." (PMID 35397606, 2022).